CD200 (CD200 molecule)
Diseases named in the same sentence as CD200 in open-access papers (continued):
Sharing a sentence is not in itself a finding about the gene and the disease.
breast tumor (5 papers, 2014 to 2025). "Growth and metastasis of a highly aggressive metastatic variant (4THM) of the breast tumor 4T1 was reported to be refractory to attenuation of CD200:CD200R interactions in CD200R1KO mice." (PMID 25409195, 2014). "In line with this, we conducted a study detailing the lymphocyte subsets, as well as their expression of immune checkpoint proteins (CD200R/CD200 and PD-1/PD-L1), infiltrating breast tumors." (PMID 39858472, 2025). "CD200-overexpressing transgenic mice (CD200tg mice) exhibit accelerated tumor growth following injection of EMT6 breast tumor cell lines compared with that in control mice." (PMID 37894750, 2023). "Blockade of CD200 expression by an anti-CD200 monoclonal antibody attenuated tumor volume in mice injected with EMT6 breast tumors and decreased tumor metastasis." (PMID 37894750, 2023). "Cell-surface CD200 expression by mouse EMT6 breast tumor cells increased primary tumor growth and metastasis to the draining lymph nodes (DLN) in normal (WT) BALB/c female recipients, while lack of CD200R1 expression in a CD200R1-/- host negated this effect." (PMID 28234914, 2017). "We have previously reported that cell-surface CD200 expression by mouse EMT6 breast tumor cells increased primary tumor growth and metastasis to the draining lymph nodes (DLN) in both WT and CD200tg BALB/c female recipients." (PMID 28234914, 2017). "The adaptive immune checkpoints BTNL9 and VTCN1 and the innate immune checkpoints CD200 and SIRPA were downregulated in breast tumor tissues while the metabolic immune checkpoints ADORA2A and TDO2 were upregulated in breast tumor tissues." (PMID 33932112, 2021).
cutaneous squamous cell carcinoma (5 papers, 2020 to 2024). "In cutaneous squamous cell carcinoma, the high expression of CD200 has been associated with a poor prognosis." (PMID 39795972, 2024). "Similarly, in cutaneous squamous cell carcinoma, CD200 expression levels were associated with tumor grade and clinical stage where patients with high CD200 expression had shorter overall survival (31.3 months) relative to patients with low expression (41.9 months)." (PMID 38137547, 2023). "CD200 expression reportedly plays a prometastatic role in cutaneous squamous cell carcinoma (cSCC), and metastasis was induced through upregulation of the cysteine protease cathepsin K (Ctsk) in CD200-positive cSCC." (PMID 37894750, 2023). "Overexpression of CD200 was observed in cutaneous squamous cell carcinoma and myelodysplastic syndrome, suggesting that CD200 could also be used as a prognostic tumor marker." (PMID 37771549, 2023).
endometriosis (5 papers, 2020 to 2025). The growth of functional endometrial tissue in anatomic sites outside the uterine body. "In endometriosis patients, CD200 expression is upregulated in lesional stromal cells and in the blood and 17β-estradiol treatment of stromal cells in culture increased expression of CD200." (PMID 36738455, 2023). "The only report to date on the role of CD200 in endometriosis indicates that the accumulation of the soluble receptor is elevated in the eutopic, secretory phase endometrium in women with endometriosis." (PMID 35805112, 2022). "Additionally, our study showed that there was a statistically lower concentration of the soluble form of CD200 in the peripheral blood plasma in the group of women with endometriosis compared to the control group." (PMID 35805112, 2022). "Their study suggested that CD200 might be a potential therapeutic target and prognostic factor, both in cancer and endometriosis." (PMID 35805112, 2022). "Thus, the Signal Regulatory Protein-α (SIRP-α), a phagocytosis inhibitory receptor, and the CD200 receptor (CD200R), which together with its ligand CD200 form an immunosuppressive complex, are significantly overexpressed in pMφ of women with endometriosis." (PMID 34639133, 2021). "An increased expression of CD200 correlates with reduced phagocytic activity and decreased CD36 expression in endometriosis (human)." (PMID 40508002, 2025). "A strong positive correlation was observed between the stage of endometriosis and the percentage of CD8+CD200 T lymphocytes and CD8+CD200R T lymphocytes." (PMID 35805112, 2022). "Patients with deep infiltrating endometriosis had a higher expression of CD19+/CD200+ B lymphocytes and CD8+/CD200+ T lymphocytes (p = 0.00034 and p = 0.00027, respectively)." (PMID 32967175, 2020). "In patients with endometriosis treated for infertility, a negative correlation was noted between the percentage of CD3+CD16+CD56+ NK cells and CD8+CD200 T cells, CD19+CD200 B cells and CD8+CD200R T cells." (PMID 35805112, 2022).
ischemic stroke (5 papers, 2018 to 2025). A stroke disorder caused by obstruction of blood flow to the brain, due to thrombotic (local blood clot formation) or embolic (due to a blood clot or other material traveling from another site) event. "Experiments in transient middle cerebral artery occlusion (tMCAO) in rats revealed that CD200 in the ischemic core decreased rapidly compared to the contralesional healthy hemisphere in the first 48 h after ischemic stroke." (PMID 37464832, 2023). "We only used CD200Fc to enhance CD200R1 expression after stroke, and CD200 or CD200R1 knockout mice were not used to mechanistically study the role of the CD200‐CD200R1 signaling pathway in neuroinflammation induced by ischemic stroke." (PMID 33067924, 2020).
neuroendocrine tumors (5 papers, 2019 to 2025). "A trend for clinical benefit among participants with high CD200 tumor expression was observed in a preliminary analysis of the phase 2a portion of this trial, particularly in neuroendocrine neoplasms and renal cell carcinomas." (PMID 39651931, 2025). "CD200, a marker for hematopoietic neoplasms, has recently become of interest for neuroendocrine neoplasms." (PMID 36674939, 2023). "That study reported that the percentage of CD200 positive neuroendocrine tumors can be as high as 87%, but was underpowered for lung LCNEC tumors." (PMID 33804482, 2021). "CD200 has been recently indicated as a robust marker of well-differentiated neuroendocrine neoplasms." (PMID 30132130, 2019). "In fact, a recent study pointed out that neuroendocrine tumors show strong immunostaining for CD200, and suggested that this marker was very sensitive for PanNET, with complete sensitivity (100%) for G1 and high sensitivity (83%) for G2 cases." (PMID 30132130, 2019). "We immunostained for CD200 22 solid pseudopapillary neoplasms (SPNs), 8 acinar carcinomas (ACs), 2 pancreatoblastomas (PBs), 138 neuroendocrine tumors (PanNETs), and 48 ductal adenocarcinomas." (PMID 30132130, 2019). "While research is still limited in this field, several authors have demonstrated that CD200 could be a sensitive immunohistochemical marker for neuroendocrine neoplasms of various sites." (PMID 36674939, 2023). "Notably, a recent report has shown that CD200 is expressed by neuroendocrine neoplasms of any anatomical site, including pancreatic neuroendocrine tumors (PanNETs)." (PMID 30132130, 2019).
psoriasis (5 papers, 2019 to 2026). An autoimmune condition characterized by red, well-delineated plaques with silvery scales that are usually on the extensor surfaces and scalp. "However, the CD200 pathway is reduced in psoriasis, resulting in a loss of immune control, and increased neutrophil recruitment in mouse models." (PMID 35759230, 2022). "Conversely, recent studies showed elevated soluble CD200 in psoriasis patient blood, tempting speculation that the reduced cell‐associated CD200 in skin, may be caused by enhanced CD200 cleavage." (PMID 35759230, 2022). "The differential expression of c‐JUN and JUNB in CD200+/K15+ bulge HF‐SCs in human samples of psoriatic plaques directed us to explore the potential causal contribution of epidermal stem cell populations to the initiation and development of psoriasis." (PMID 31556482, 2019). "Therefore, the reduced CD200 in PN skin may be an underlying factor contributing to psoriasis susceptibility." (PMID 35759230, 2022). "Here we show reduced CD200, and CD200R1 signaling in PN skin which, in a mouse model of psoriasis, results in enhanced severity associated with increased skin thickening, CCL20 levels, and neutrophil recruitment." (PMID 35759230, 2022). "Previous work showed that providing exogenous CD200 reduced psoriasis‐like skin inflammation by inhibiting macrophage activity." (PMID 35759230, 2022). "An experimental mouse model of psoriasis however reported up-regulation of CD200R upon subcutaneous injection of recombinant CD200, a change that was accompanied by symptom amelioration." (PMID 32203537, 2020). "Consequently, there was a significant reduction in the percentage of CD2+MHC-II+CCR2+ myeloid precursors interacting with CD200+ fibroblasts in individuals with PsA compared to in those with psoriasis." (PMID 41482544, 2026). "However, in contrast to our data, systemic CD200 provision reduced cytokines in a psoriasis model and cultured macrophages." (PMID 35759230, 2022). "In conclusion, we highlight CD200R1:CD200 as a pathway that might be targeted to dampen inflammation in patients with psoriasis." (PMID 35759230, 2022). "Therefore, investigating the role of CD200R1 in addition to CD200 is crucial for understanding the role of this receptor‐ligand family in regulating the human disease, psoriasis." (PMID 35759230, 2022). "Exogenous CD200 dampens inflammation in a similar murine psoriasis model, suggesting there may be therapeutic benefit to manipulating this pathway." (PMID 35759230, 2022). "Here we show that CD200 is reduced in uninvolved psoriasis skin." (PMID 35759230, 2022). "Enhanced expression of sCD200 in psoriasis could be a consequence to the ongoing inflammatory response, characterized by an increased release of TNFα and INFγ, both of which are potent inducers of CD200 expression." (PMID 32203537, 2020). "Since CD200 over expression in psoriasis is likely mediated by higher levels of TNFα and INFγ, both of which contribute to the cytokine inflammatory storm in psoriasis, then difference in expression levels among different severities could be explained." (PMID 32203537, 2020). "We reveal that CD200 and signaling via CD200R1 are reduced in non‐lesional psoriasis skin." (PMID 35759230, 2022). "Therefore, the reduced CD200 and CD200R1 signaling in PN skin will likely lead to increased neutrophil accumulation in response to a challenge, enhancing the immune response and potentially promoting the onset of a psoriasis flare." (PMID 35759230, 2022). "However, the lack of correlation between disease severity and CD200 level is possibly due to the contribution of other several effector cytokines in the inflammatory process of psoriasis and consequently its clinical severity." (PMID 32203537, 2020). "Interestingly, bulge HF‐SCs labeled with CD200 did not express TSLP in psoriasis patients, neither lesional nor non‐lesional scalp, while sub‐bulge ORS increased its expression in lesional HFs." (PMID 31556482, 2019).
rheumatoid arthritis (5 papers, 2012 to 2025). A chronic, systemic autoimmune disorder characterized by inflammation in the synovial membranes and articular surfaces. "Interestingly, within rheumatoid arthritis, a chronic inflammatory autoimmune disorder, pro‐resolving CD200+ fibroblasts arise during the resolution of inflammation in the synovium." (PMID 41211809, 2025). "The distinction between the pathophysiology of osteoarthritis and rheumatoid arthritis may explain why CD200 based treatment failed in the osteoarthritis model despite being successful in the rheumatoid model." (PMID 35359946, 2022). "Indeed, the use of infliximab and methotrexate in rheumatoid arthritis patients resulted in up regulation of both peripheral CD200 and CD200R, a change that correlated to the clinical improvement of the disease as evidenced by reduced disease severity scores." (PMID 32203537, 2020). "This dichotomy between CD200 and CD200R expression has been described in several other Th17 mediated diseases including SLE, inflammatory bowel disease and rheumatoid arthritis." (PMID 32203537, 2020). "Regarding the status in other inflammatory Th17 mediated diseases, both CD200 and CD200R correlated negatively with rheumatoid arthritis severity (expressed as DAS28) while they did not correlate with SLE severity scores." (PMID 32203537, 2020).
schizophrenia (5 papers, 2014 to 2022). A major psychotic disorder characterized by abnormalities in the perception or expression of reality. "In the offspring at postnatal day 7 (PND7), we examined the impact of MIA on the mRNA and protein expression of CX3CL1, CD200 and their receptors in the hippocampus and frontal cortex, which are areas of the brain distinctly affected in schizophrenia." (PMID 32829711, 2020). "Hence, further research is required to fully define and explain the involvement of quetiapine and other antipsychotics in Cx3cl1-Cx3cr1 and/or Cd200-Cd200r axes modulation and inflammatory processes in the LPS-based model of schizophrenia-like disturbances." (PMID 36139363, 2022).
squamous cell carcinoma (5 papers, 2012 to 2023). A carcinoma arising from squamous epithelial cells. "Expression of CD200 has been implicated in multiple types of human cancer including squamous cell carcinoma." (PMID 23632869, 2013). "However an adverse effect of CD200-CD200R blockade is also possible as CD200 expression increases with progression of squamous cell carcinoma, suggesting that CD200-expressing tumour cells engage and modulate tumour associated myeloid-derived suppressor cells." (PMID 27212807, 2016). "Overexpression of CD200 has been reported in a number of malignancies and on cancer stem cells and this molecule may play roles in local tumor invasion as well as augments the metastatic capacity of squamous cell carcinoma." (PMID 23632869, 2013). "A study that investigated CD200 and CD200R expression in the TME of human squamous cell carcinoma (SCC) found that high levels of CD200 were expressed on endothelial cells lining the cancer’s vasculature." (PMID 36756156, 2023).
systemic lupus erythematosus (5 papers, 2012 to 2021). An autoimmune multi-organ disease typically associated with vasculopathy and autoantibody production. "This study aimed to assess the function of CD200/CD200R1and impact of CD200-Fc on dendritic cells in lupus-prone NZB/WF1 mice." (PMID 27545083, 2016). "In the present study, we conducted new observations by selecting NZB/WF1 mice and examining the therapeutic potential of the recombinant CD200-Fc protein in lupus-prone mice." (PMID 27545083, 2016). "We therefore evaluated the functional status of CD200/CD200 receptor 1 (CD200R1) interactions in subjects with systemic lupus erythematosus (SLE)." (PMID 22621248, 2012). "Abnormal expression of CD200/CD200R1 may contribute to the immunologic abnormalities in patients with systemic lupus erythematosus (SLE)." (PMID 27545083, 2016). "In addition, this down-regulation of CD200R1 expression on DCs was also noted in lupus-prone mice along with elevated levels of anti-dsDNA Abs, which could be reversed by CD200-Fc treatment possibly through reducing the productions of IL-6 and IL-10 from DCs." (PMID 31597242, 2019). "This study suggests that the immunosuppressive CD200/CD200R1 signaling pathway might be involved in the immunopathology of NZB/WF1 mice; the present results merit further exploration of agents that can modulate the CD200/CD200FR1 pathway as a therapy for human lupus." (PMID 27545083, 2016). "Furthermore, the serum CD200 level negatively correlated with the serum complement 3 level (r = -0.45, P = 0.014), but not the Systemic Lupus Erythematosus Disease Activity Index score or the levels of serum B-cell activating factor belonging to the TNF family, IL-6, IFNα, or anti-dsDNA (P > 0.05)." (PMID 22621248, 2012).
acute lymphoblastic leukemia (4 papers, 2016 to 2023). Leukemia with an acute onset, characterized by the presence of lymphoblasts in the bone marrow and the peripheral blood. "In addition to its diagnostic value, CD200 has been shown to have a prognostic role in diseases such as in acute lymphoblastic leukaemia." (PMID 37822353, 2023). "We aim at investigating the expression pattern of CD200 on leukemic B cells and the correlation of CD200 expression with various clinical and laboratory findings in 62 newly diagnosed acute lymphoblastic leukemia patients." (PMID 36673136, 2023). "We will correlate CD200 expression with various clinical and laboratory findings in newly diagnosed acute lymphoblastic leukemia patients." (PMID 36673136, 2023). "Interestingly, the BTLA/CD200 deletions have recently been reported in adult B cell precursor acute lymphoblastic leukemia (ALL) pts." (PMID 27933341, 2016).
B-cell neoplasm (4 papers, 2016 to 2023). A group of heterogeneous lymphoid tumors generally expressing one or more B-cell antigens or representing malignant transformations of B-lymphocytes. "Several studies have confirmed that CD200 immunophenotyping was of utility in the differential diagnosis of B-cell neoplasms." (PMID 26910908, 2016). "The addition of CD200 to flow cytometry marker panels addressing the diagnosis of this heterogenous group of B cell neoplasms may be particularly helpful in distinguishing some disease entities, in particular CLL and MCL, whose clinical behavior and prognosis are quite different." (PMID 33324560, 2020).
bladder cancer (4 papers, 2020 to 2023). "We conclude that an immunotherapy/anti‐CD200 combination might offer a promising therapeutic option for bladder cancer patients with high proportions of PD1hi CD200hi CD4+ exhausted T cells." (PMID 37313656, 2023). "Furthermore, CD200 expression also promoted EMT in bladder cancer cells." (PMID 38137547, 2023). "Finally, our findings suggest that immunotherapy combined with anti‐CD200 drugs might be a promising therapeutic option for bladder cancer patients with high proportions of PD1hi CD200hi CD4+ exhausted T cells." (PMID 37313656, 2023).